NOS2 (nitric oxide synthase 2)
Diseases named in the same sentence as NOS2 in open-access papers (continued):
Sharing a sentence is not in itself a finding about the gene and the disease.
tumor (continued). "This evidence suggests that while NOS2 and COX2 control the migration of CD8+ T cells, CD4+ T cell mobility is unaffected but could augment TEff function at the tumor margin." (PMID 40663402, 2025). "However, when CD8+ T cells penetrate the tumor nest, NOS2/COX2 levels in the entire tumor are low, suggesting their role(s) in CD8+ T cell restriction and exclusion from the tumor core." (PMID 40663402, 2025). "Overall, these data support the computational prediction that NOS2 (iNOS) serves as a shared molecular target of both EPO and SPO and demonstrate that both extracts can downregulate iNOS transcription and NO production in inflammatory and tumor cell contexts." (PMID 41598205, 2025). "In favor of this, preclinical models involving inhibition of CCL2, NOS2, and LCN2 pathways have shown anti-tumor effects and may be explored to improve IL6 inhibitory strategies after PD-L1 treatment failure." (PMID 39663510, 2025). "Furthermore, tumor-derived exosomes enhance glucose uptake via the TLR2 and NF-κB pathways, leading to increased nitric oxide synthase 2 (NOS2) levels, which inhibit mitochondrial oxidative phosphorylation." (PMID 40028322, 2025). "High COX2 rather than NOS2 suggests the importance of PGE2 from the tumor in maintaining the exclusion of CD8+ T cells." (PMID 40663402, 2025). "Indeed, elevated NOS2 and COX2 at tumor margins are close to stroma-restricted CD8+ T cells and lymphoid aggregates, whereas, in cold regions (i.e., low CD8+ T cell counts) and immune deserts, COX2 is present." (PMID 40663402, 2025). "This progression from an inflammatory region to immune desert status suggests that NOS2 and COX2 could provide therapeutic targets that limit the formation of tumor immune deserts." (PMID 40663402, 2025). "This treatment dramatically increases inducible NO synthase (iNOS/NOS2) activity, thus NO, resulting in a synergistic effect of resistance to cell death pathways (primarily apoptosis) while simultaneously promoting tumor growth, migration, and invasiveness." (PMID 39996790, 2025). "Thus, leukocyte-based immunosuppressive cells are favored in the presence of elevated TEff cell infiltration in inflamed tumors, while NOS2 and COX2 predominate in immune cold or immune desert regions, indicating distinct roles during tumor immunosuppression." (PMID 40663402, 2025). "In our model, NOS2 was impressively decreased in S1.1 cells, indicating that NDM29 may act also to ameliorate the tumor microenvironment and the inflammatory status." (PMID 40743051, 2025). "We found that the increased number of Ly6Clow macrophages in CD244fl/flLysMcre mice was accompanied by a significant upregulation of anti-tumorigenic macrophage markers and cytokines, including CD80, NOS2, IL6, and IFNB1, in CD11b+ sorted tumor-infiltrating macrophage populations." (PMID 38424542, 2024). "As opposed to the conditioned medium from Sema3a deficient cells, the conditioned medium from SEMA3A expressing tumour cells significantly induced Arg1 expression without eliciting Nos2 expression." (PMID 38670629, 2024). "Stroma-restricted lymphoid aggregates average 500 to 1,000 μm from NOS2+ and/or COX2+ tumor edges." (PMID 39356141, 2024). "Consistent with the reduced population of CD206high TAMs, the amount of Arg1 mRNA was reduced in tumor tissues from mKO mice compared to WT mice, although we did not detect a difference in the mRNA expression of Nos2 in tumor tissues from these mice." (PMID 38308188, 2024). "Similar concerns arise when targeting NFκ-B and other components of the NOS2 and COX2 cellular signaling pathways, as this may interfere with critical anti-tumor pathways." (PMID 38892290, 2024). "In contrast, tumors from surviving patients at 5-year postdiagnosis exhibited low, sporadic tumor NOS2/COX2 expression and elevated CD8+ T-cell infiltration into the tumor, which promotes tumor eradication by perforins and granzyme B in a cell-to-cell contact manner." (PMID 39356141, 2024).
tumor (continued). "Immunohistochemistry for F4/80, NOS2, and CD206 was performed to investigate the TAM population and polarized phenotype localized in the intratumoral areas and peritumoral stroma of each tumor in 16-week-old PyMTWT and PyMTSB2−/− mice." (PMID 38956496, 2024). "We also checked the impact of primary tumour size, the status of lymph nodes metastasis and distant metastasis, as well as the grading of histological malignancy on the level of methylation of SOD2 and NOS2 promoter regions." (PMID 37660159, 2023). "M-MDSC from 4T1 tumor-bearing mice with induced tumor site infiltration has been reported to promote tumor metastasis by inducing nitric oxide synthase 2 (NOS2) production and activating STAT1 and STAT3 signaling pathways in tumor cells to induce EMT and CSCs phenotypes." (PMID 37465670, 2023). "Taken together, this study shows the strength of spatial localization analyses of the CD8/NOS2/COX2 landscape, how it shapes the tumor immune microenvironment and the selection of aggressive tumor phenotypes in distinct regions that lead to poor clinical outcomes." (PMID 38187532, 2023). "Lack of Nos2 also decreased the proportion of tumor-specific (OT-I) CD44+ cells circulating in the blood." (PMID 36574610, 2023). "In contrast, NOS2 weak signal intensities were significantly elevated in the stroma but not tumor, while COX2 weak signal intensity was higher in tumor but not stroma." (PMID 37169743, 2023). "Thus, NOS2 and COX2-expressing cells are spatially localized in distinct inflammatory regions of the tumor." (PMID 37169743, 2023). "According to the scRNAseq results, IFNγ and IL1β/TNFα are necessary to induce the highest levels of NOS2 and COX2 expression, which suggests that lymphoid cells could be a contributing factor in the tumor." (PMID 37169743, 2023). "The expression of NOS2 in CD24 + CD133 + liver CSC promotes NO/cGMP/PKG, driving Notch signaling and stemness characteristics in vitro and in vivo, and accelerates HCC initiation and tumor formation in the murine HCC tumor." (PMID 37958916, 2023). "Some genes function as tumor suppressor including PLA2G2A, PI3, and NOS2." (PMID 36944972, 2023). "Moreover, many genes related to an accumulation of T cells (Cd8a, Cd3e, Cd4), inflammations (Cxcl9, Tnf, Ifng), and a subset of M1-macrophage (Ciita, Nos2, Cd86) have elevated in anti-PD-1 antibody-treated IL-34KO CT26 tumor." (PMID 36798830, 2023). "In syngeneic models of CRC and HCC, exoASO-STAT6 alone induces nitric oxide synthase 2 (NOS2) expression, an M1 macrophage marker, leading to remodeling of the tumor immunosuppressive microenvironment and activating of a CD8 T-cell–mediated adaptive immune response." (PMID 36922504, 2023). "The lack of NOS2 in T cells also significantly reduced transendothelial migration in vitro and tumor infiltration in vivo." (PMID 36574610, 2023). "Indeed, the modifications induced by the doxorubicin/GTN combination on the tumor microenvironment and on the PMN-MDSCs (FATP2, CXCR2, NOS2, S100A9) are in favor of reprogramming these cells towards a less immunosuppressive PMN type phenotype." (PMID 37370739, 2023). "While data here clearly demonstrate that maximum human NOS2 expression is induced by IFNγ, IL1β, and TNFα, identical to that in murine tumor cells, human macrophages do not activate NOS2 with IFNγ or LPS." (PMID 37169743, 2023). "qRT-PCR analysis of bulk tumor RNA indicated that ACT+MS-275 treatment downregulated ARG1, NOS2, and TGFB1 expression, which may prohibit Treg expansion." (PMID 35972798, 2022).
tumor (continued). "Prostaglandin E2 (PGE2) is a critical product of cyclooxygenase 2 (COX-2), which is overexpressed in most human cancers, affects tumor progression and immunosuppression, and stimulates arginase-1 (ARG-1) and nitric oxide synthase (NOS)-2 secretion from MDSCs24." (PMID 35058524, 2022). "The differential expression of NOS2 and ALOXE3 in tumor tissues and normal tissues suggests that NOS2 and ALOXE3 may be involved in the regulation of tumorigenesis and progression." (PMID 35265525, 2022). "We then analyzed the associations between CXCL2 expression and classical macrophage phenotype markers of M0 (undifferentiated) (AIF1), M1 (anti-tumor) (IL12A, TNF, NOS2, PTGS2) and M2 (tumor-promoting) (IL10, CD163, TGFB1, CSF1R) in TCGA-LIHC cohort with Spearman’s rank correlation test." (PMID 36276119, 2022). "Particularly, in addition to the tumor immune escape pathway, genetic markers belonging to the cytokines/interleukins, including CXCL8, CCL5, CCR5 and angiogenic mediators including IGF1, IRF3, NOS2, appear to be the most promising." (PMID 36432658, 2022). "In contrast, Trib1mKO reduced infiltration of PV TAMs, but did not alter the number of NOS2 positive macrophages in the tumor." (PMID 35664073, 2022). "Our results showed that 1.0 g/kg BJIKT administration dramatically decreased the ARG-1 expression in tumor-infiltrating MDSCs, but not significantly in NOS2 expression." (PMID 35873573, 2022). "Since tumor-induced exclusion/immunosuppression involves the activation of multiple signaling pathways, pharmacological inhibition would be effective in this regard, including pathways of Wnt/β-catenin, PI3K-Akt, IFN-β/NOS2, CSF-1, TGF-β, adenosine, and IDO." (PMID 34194441, 2021). "As a result of the examination of the tumor microenvironment, decreased inflammatory cell (CD11b+ and F4/80+) uptake, decreased expression of cytokines (IL1α/β, IL6, CCL2, CXCL5, and TNFα) and pro-inflammatory enzymes (COX-2, and NOS2) were determined." (PMID 34073059, 2021). "Tumor expression of NOS2 was insignificantly (ρ = −0.35, p = 0.072) and these of PRMT2 (ρ = −0.41, p = 0.036) and ASL (ρ = −0.41, p = 0.029) were significantly inversely correlated with depth of tumor invasion (T1/2–T3–T4)." (PMID 34439753, 2021). "The known M1-inducing combination of IFN-γ and LPS induced the expression of Nos2, but no stimulation of Nos2 by tumor CM was observed." (PMID 34680504, 2021). "In a hypoxic TME, tumor-induced macrophage polarization (from M1 to M2) occurs via increased nitric oxide (NO) and decreased arginine in hypoxia, as reflected by transcript levels of arginase 1 (ARG1) and nitric oxide synthase 2 (NOS2) in PDAC models." (PMID 32664564, 2020). "Metabolic reprogramming in CRC includes overexpression of DDAHs and PRMTs in addition to ARG1 and NOS2 and is not restricted to tumor tissue but can be modulated by novel oxicam analogues." (PMID 32932854, 2020). "Possibly, as observed by increases of Tnfa, Ifng, and Nos2 expression, it could well be that in HSD fed animals besides other innate immune cells like macrophages, tumor-infiltrating MDSCs themselves became more pro-inflammatory and anti-tumoral." (PMID 31214164, 2019). "After exosome administration, NOS2 expression was detected in the axillary LNs of tumor-bearing mice but not in the axillary of healthy mice without tumors, and upregulated in the metastatic LNs." (PMID 29484119, 2018). "Yet for RENCA, tumor progression also yielded an overall increase in suppressive myeloid cell (MDSC) density, as well as increased expression of genes that drive monocytic MDSC immunosuppression (NOS2/iNOS, MIF, and TGFβ2)." (PMID 30388137, 2018). "In addition to TAM and T lymphocytes that have a key role in tumor progression, the myeloid cell population can suppress T-lymphocyte activity by the expression of arginase 1 (ARG1) and nitric oxide synthase 2 (NOS2)." (PMID 30545144, 2018).
tumor (continued). "Interestingly, NOS2, a target of DUSP4, and DUSP4, both factors that stimulate tumour migration and invasion, are regulated by GFAP." (PMID 29152145, 2017). "Clearly, NOS2 mRNA showed a positive correlation with antigen presentation and immune markers only in PDAC (last row) supporting that it plays a role in PDAC immunosuppression as the T-cell numbers increase in the tumor." (PMID 27762323, 2016). "Furthermore, we confirmed the anti-tumor effect of NEAPP-AM on other EOC cell lines (ES-2, SKOV3, and NOS2)." (PMID 25184103, 2014). "Surprisingly, treatment with L-NAME, an inhibitor of NOS2, did not significantly affect body weight and tumor burden or lifespan despite decreased serum levels of nitric oxide to normal baseline." (PMID 23408900, 2013). "Ultrastructural labeling of inducible NOS (NOS2) immunoreactivity in metastatic liver tumor tissues determined by using electron microscopy and PAP immunocytochemical techniques showed that almost all of tumor vessel EC was positively stained with NOS2." (PMID 23691268, 2013). "We could observe a significant statistical correlation between the amount of NOS2+ and CD163+ macrophages (P<0.0001), demonstrating the parallel presence of macrophages with both M1 and M2 phenotypes at the tumor invasive front." (PMID 23077543, 2012). "Furthermore, an increased infiltration of both NOS2+ and CD163+ macrophages at the tumor front was correlated to a significantly improved prognosis." (PMID 23077543, 2012). "Cytoplasmic and nuclear staining for COX-2 and NOS-2 was observed in both tumor cells and non-tumor connective tissue cells, including sinusoidal endothelial cells." (PMID 20716344, 2010). "NOS2 and COX2 form a reciprocal feed-forward circuit in which NO, prostaglandin E2 (PGE2), interleukin (IL)-6, and IL-8 reinforce one another, driving tumor-promoting inflammation, immunosuppression, angiogenesis, and metastasis while depleting nutrients and acidifying the tumor interstitial fluid." (PMID 42248132, 2026). "The lack of both tumor infiltrating lymphocyte (TIL) aggregates and NOS2+ tumor edges observed in the type III immune desert regions is also associated with lower COX2 expression and is consistent with NOS2/COX2 feed-forward signaling." (PMID 40663402, 2025). "Moreover, NOS2/COX2 inhibition produced profound changes in antitumor immunity that reduced both metastatic burden and tumor growth and led to increased cures and resistance to tumor rechallenge in the aggressive 4T1 mouse model." (PMID 40663402, 2025). "However, these experiments lacked the spatial organization of the tumor immune microenvironment in situ and how it can be influenced by regional tumor NOS2 and COX2 expression." (PMID 39356141, 2024). "Moreover, spatial analysis of the CD44v6 and EpCAM cancer stem cell (CSC) markers within the CD8/NOS2/COX2 expression landscape revealed positive correlations between EpCAM and inflamed stroma-restricted CD8+NOS2+COX2+ phenotypes at the tumor/stroma interface in deceased patients." (PMID 38187532, 2023). "Although IL4Rα-negative MDSC had lower Arg-1 and NOS2 expression before and after chemoradiotherapy, the possibility remains that they may transform into more suppressive cells upon entering the tumor microenvironment." (PMID 37554225, 2023). "Nos2 deletion did not affect OCR or in vitro killing of tumor cells." (PMID 36574610, 2023). "However, statistical analysis did not reveal that the expression of NOS2 was correlated with gender, age, tumor location, tumor differentiation, or TNM stage (P > 0.05)." (PMID 35265525, 2022).
tumor (continued). "Importantly, we found that myeloid cells from MCA203-W30L tumor-bearing mice expressed lower level of both ARG1 and NOS2 enzymes as compared to the control, that could potentially explain their reduced suppressive activity." (PMID 34675917, 2021). "In addition, we found that the number of neutrophils continuously increased, and these cells expressed high levels of Mmp9, Prok2, Vegfa, and Nos2, but not tumor suppressors." (PMID 32709844, 2020). "Additionally, only co-transfer of CD8+ T cells with wild-type macrophages, but not with Nos2−/− macrophages, yielded T-cell homing to the tumor, and consequently led to tumor rejection." (PMID 30082427, 2018). "Although there were fewer macrophages in the clodronate-treated lungs, the ratio of ArgI to NOS2 remained constant in the remaining cells indicating that the remaining tumor microenvironment and not macrophage depletion continued to affect the programing of the remaining macrophages." (PMID 25505466, 2014). "An alternative explanation for the increased NOS2 expression in vascular endothelium and all NOS isoforms immunoreactivity in other cells in metastatic liver tissue is that a large number of noncontractile types of fibroblasts and/or myofibroblast-like cells are present in tumor tissues." (PMID 23691268, 2013). "Analysis of pro-inflammatory phenotype in tumor samples and in cancer stem cells from GBM was conducted at the mRNA and protein levels by studying the expression of the membrane receptors RAGE and P2X7R, the inducible enzymes COX2 and NOS2, and the acute phase protein PTX3." (PMID 21489226, 2011). "Interestingly, after the same treatment with the model, Nos2 mRNA expression level showed no significant change in tumor cells while showed significant downregulation in CAFs (downregulated to ca. 0.3), indicating a CAF‐specific regulation effects of hydrogen gas." (PMID 38757665, 2024). "The reduced numbers of metastases seen here in mice lacking myeloid NOS2 suggest that myeloid NO may contribute to early stages of tumor establishment, particularly as the size of metastatic lesions was not significantly different between wild type and NOS2 mutant mice." (PMID 34054802, 2021). "Additionally, Nos2-/- macrophages could not co-transfer with CD8 + T cells yield T-cell homing to the tumor and tumor rejection." (PMID 34095122, 2021). "Many infiltrating macrophages are positive for M2-macrophage marker arginase (ARG1) but negative for M1-macrophage marker nitric oxide synthase 2 (NOS2), indicative of a tumor-supportive microenvironment." (PMID 38422022, 2024). "The fact that REG does not reduce Nos2, a M1-TAM marker, in contrast to Mrc1, is an indicator of an increased M1:M2 ratio impeding tumor growth." (PMID 37013652, 2023). "To assess the functional consequences of NOS2 mediated induction of EMT-related genes, we performed in vitro tumour invasion assay in presence and absence of NOS2 donor, DPTA." (PMID 28382931, 2017). "Our extended study by using postembedding triple immunogold labeling techniques showed that the clusters of NOS2 positive, but no NOS3 and ET-1 immunopositive containing gold particles were seen in tumor vessel endothelium." (PMID 23691268, 2013).